IRF8 (interferon regulatory factor 8)
Diseases named in the same sentence as IRF8 in open-access papers (continued):
Sharing a sentence is not in itself a finding about the gene and the disease.
tumor (continued). "IRF8 upregulation in tumor cells inhibited the generation of Th17 cells in vitro, and this may be mediated by the downregulation of RORγt." (PMID 28537908, 2017). "In our study, KLF4 and IRF8 were up-regulated TFs, and IRF8 was a tumor suppressor gene." (PMID 27405725, 2016). "While IRF8 is recognized as a tumor suppressor gene in certain hematopoietic malignancies, in solid tumor models, these additional studies underscore previously unrecognized anti-neoplastic activities for IRF8 perhaps distinct from its tumor suppressor roles." (PMID 26008967, 2015). "Moreover, our findings expand our current understanding of how MMP3 is regulated, as well as how IRF8 functions in tumor biology." (PMID 26008967, 2015). "IRF8 expression appeared to suppress colony formation, leading to the conclusion that IRF8 may act as a tumor suppressor." (PMID 25120651, 2014). "In contrast, we showed that TSA treatment of mice bearing the IRF8-deficient tumor cells failed to promote significant antitumor effects, suggesting that ‘tumor response to therapy’ in vivo was IRF8-dependent." (PMID 23028998, 2012). "Moreover, we showed that TSA-mediated suppression of tumor growth in vivo was dependent on tumor expression of IRF-8." (PMID 23028998, 2012). "and 2) Is IRF-8 expression required for HDACi to promote antitumor effects in tumor-bearing mice?" (PMID 23028998, 2012). "Thus, in this cell line model of varying tumor aggressiveness, IRF-8 response to a single or combination HDACi-based treatment regimen correlated with tumor phenotype." (PMID 23028998, 2012). "We hypothesized that IRF-8 expression in tumor cells is an important molecular component for their susceptibility to HDACi-induced apoptosis." (PMID 23028998, 2012). "We reasoned that rescue of IRF-8 expression in tumor cells may improve responses to anti-neoplastic therapies, such as chemotherapy or biologic (Fas)-based immunotherapy." (PMID 23028998, 2012). "Although DP and TSA each induced IRF-8 expression in CMS4 tumor cells, TSA was selected for subsequent experiments based on earlier work that showed that TSA treatment could restore Fas sensitivity in tumor cells." (PMID 23028998, 2012). "However, a single-cell study revealed that one IRF8+NR1H2 macrophage cluster and another CD274 cluster exhibited similar gene expression and were similar to M1 macrophages during the anti-tumor immune response of early-stage OC, and IRF8 and CD274 were upregulated in an activation-dependent manner." (PMID 41601649, 2026). "Also, the decreased tumor weight and volume were abolished after Irf-8 knock-down." (PMID 41315179, 2025). "In addition to the direct regulation of immune cells, the functional heterogeneity of specific transcription factors significantly affects tumorigenesis, with the role of IRF8 being particularly representative, as its function varies completely depending on the type of tumor cells." (PMID 41368628, 2025). "Interestingly, we observed upregulation of several interferon regulatory factor (Irf) family members including irf7 and irf8 in p53EPS tumor-burdened brains, suggesting potential roles for these master regulators of inflammation on immune-related responses during p53EPS tumorigenesis in vivo." (PMID 39052000, 2024). "Indeed, the most interesting result was related to the evidence that GBM cells, along with tumor progression, showed the upregulation of genes, such as interferon regulatory factor 8 (IRF-8) and chemokines belonging to the myeloid population, regardless of gene mutations and clonal selections." (PMID 36829778, 2023). "In DLBCL, IRF8-induced reduction of Th17 expansion may contribute to tumor formation." (PMID 36078039, 2022). "Moreover, IRF8 also functions as an apoptosis regulator in hematopoietic tumor cells." (PMID 36078039, 2022). "Thus, further work would be important to clarify, whether IRF8 acts predominantly as oncogene or as tumor-suppressor in human AML." (PMID 33673123, 2021).
tumor (continued). "Thus, it has been proposed that IRF8 could be acting as a tumor suppressor via mechanisms that need to be better elucidated." (PMID 33766090, 2021). "However, IRF8 expression can emanate from additional tumor-resident populations, including human tumor cells and therefore our initial findings could be influenced by TAM-independent factors." (PMID 31221219, 2019). "However, our group is also interested in testing whether combinations of IRFs (e.g., IRF5 and IRF8) can synergistically improve the anti-tumor potential we describe here." (PMID 31481662, 2019). "Additionally, we found IRF8 protein was reduced in tumor-bearing mouse MDPs, CDPs, and pre-DCs." (PMID 29593283, 2018). "Therefore, IRF8 may promote DLBCL tumor cell growth, which may inhibit the generation of Th17 cells in DLBCL patients." (PMID 28537908, 2017). "However, whether the expression profile of IRF8 in human tumor cells affects the generation of Th17 cells and survival of DLBCL patients remains unknown." (PMID 28537908, 2017). "It is possible that IRF8 may modulate the expression of surface molecules on the tumor cells or the secretion of soluble factors from these tumors, which then in a tumor-extrinsic manner suppresses RORγt in neighboring T cells and their differentiation into Th17 cells." (PMID 28537908, 2017). "Interestingly, increases in tumor growth in vivo could not be explained solely by differences in apoptotic phenotype, suggesting that additional aspects of tumor biology were influenced by IRF8 expression." (PMID 26008967, 2015). "Similarly, WT1 mediates BCR-ABL induced repression of the myeloid tumor suppressor IRF8." (PMID 26320177, 2015). "Furthermore, knockdown of oncogenic IRF4 induced the tumor suppressive activities of IRF8." (PMID 23658517, 2013). "Furthermore, IRF8 can function as a tumor suppressor in myeloid cancers." (PMID 23658517, 2013). "Taken collectively, these results show that HDACi can enhance basal or IFN-γ-inducible IRF-8 levels in tumor cell line models of varying malignant phenotypes and raise the possibility that HDACi may exert antitumor effects, at least in part, through IRF8-dependent mechanisms." (PMID 23028998, 2012). "Thus, we hypothesized that tumor-cell expression of IRF-8 is also important for response to TSA-mediated antitumor activity in vivo." (PMID 23028998, 2012). "However, the mechanisms involved in IRF-8 down-regulation in tumor cells remained unclear." (PMID 23028998, 2012). "Therefore, in our preclinical tumor model, we tested the hypothesis that IRF-8 expression is important for response to HDACi-based antitumor activity." (PMID 23028998, 2012). "Based on previous work that established that HDACi can enhance Fas sensitivity and that IRF-8 expression was required for response to Fas killing, we tested the hypothesis that tumor-cell expression of IRF-8 was required for Fas-induced death following HDACi treatment." (PMID 23028998, 2012). "We first evaluated whether HDACi affects tumor cell expression of IRF-8." (PMID 23028998, 2012). "In recurrent HGSOC, the recurrent tumor-specific DEGs IL7R, IRF8, and PTPRC displayed significant correlations with seven proteins." (PMID 41596598, 2026). "The expression levels of IL7R, IRF8, and PTPRC were significantly upregulated in recurrent tumors, compared with primary tumors, and correlated strongly with one another across both tumor types (p < 0.05)." (PMID 41596598, 2026). "Cells in the DC-C1 cluster, characterized by high expression of XCR1 and IRF8, were identified as conventional type 1 dendritic cells (cDC1s) and were predominantly enriched in NMI tumour samples." (PMID 41281745, 2025). "The findings demonstrated that IRF8 overexpression promoted an immune-active TIME and suppressed tumor progression." (PMID 39940857, 2025). "To investigate the role of TRIM63/IRF-8 axis, we primary attempted to check the effect of IRF-8 in tumor cells." (PMID 41315179, 2025).
tumor (continued). "However, the precise role of IRF-8 in tumor cells remains unclear." (PMID 41315179, 2025). "While multiple studies have examined IRF8 to have important roles in the context of myeloid cells and its tumor suppressor function through downstream STAT1 signaling, there has been limited studies of the role of IRF8 in cytotoxic T cells." (PMID 40610421, 2025). "Violin plots demonstrated significantly elevated activities of IRF5, IRF8, KLF2, TFAP2B, and MAFK in Zbp1−/− tumor cells, while E2F4 and ETV4 were preferentially activated in WT tumors." (PMID 41430036, 2025). "Four of the top 5 regulons in stromal or tumor region were overlapped, including CDX1, IRF8, HNF4A, and CREB3lL1." (PMID 38729966, 2024). "In this study, we demonstrate that PU.1, IRF8 and BATF3-mediated cell fate reprogramming of tumor cells into immunogenic cDC1-like cells in situ represents a new immunotherapeutic modality for the treatment of solid tumors." (PMID 39236156, 2024). "Our previous research showed that FOXO4, IRF8, and LEF1 were differentially expressed (via RNA sequencing) in canine OSA compared to patient-matched non-tumour tissue." (PMID 38792023, 2024). "In the study of gastric cancer, the researchers found that CD68+IRF8+M1 TAMs and CD68+CD206+M2 TAMs were closest to the tumor cells, while CD68+CD163+CD206+M2 TAMs were farthest from the tumor cells." (PMID 38279145, 2024). "Our previous research showed that FOXO4, IRF8, and LEF1 were differentially expressed (via RNA sequencing) in canine osteosarcoma compared to patient-matched non-tumour tissue." (PMID 38792023, 2024). "Two WT (MC654 and MC659) and two IRF8.KO (MC010 and MC011) cell lines were established as stable tumor cell lines." (PMID 36672246, 2023). "However, whether IRF8 regulates other cell death pathways in tumor cells is unknown." (PMID 36672246, 2023). "Hence, inducing tumor cell senescence or death (increasing IRF8 expression or radiotherapy) may increase the signal strength of cGAS/STING signaling in TIME MICs (macrophages and DCs) by phagocytosing the cytosolic dsDNA to create a proinflammatory and cytotoxic TIME." (PMID 37380989, 2023). "It will be interesting to understand the factors controlling IRF8 expression in TAMs and its function (cGAS/STING signaling activation and antigen presentation) for tumor immunotherapies to adjunct currently available ICIs." (PMID 37380989, 2023). "This analysis revealed that network hubs – the likely mediators of network function and disease – were regulated by known oncogenic transcription factors in TNBC, including IRF8 and SPI1, both correlated with survival and tumor immunogenicity in TNBC." (PMID 37781176, 2023). "The tumor suppressors ETV6, CEBPA, IRF8, and IRF1 are among the lineage-controlling master TFs found in CD141-positive monocytes enriched with SE-associated genes upregulated by cortistatin A." (PMID 37501079, 2023). "In contrast, CD68+IRF8+, CD68+CD163+CD206+ macrophages were less enriched in both tumor and stroma regions." (PMID 37723144, 2023). "The IRF8 (Interferon regulatory factor 8) and BATF (Basic Leucine Zipper ATF-Like Transcription Factor) are very crucial in developing the anti-tumour response in tumour surveillance." (PMID 35388653, 2022). "All four TAM markers were significantly and positively associated with higher TIL density (p < 0.001), higher PD-L1 expression in tumor (p < 0.001) and stromal cells (p < 0.001 for CD68, IRF8 and CD163; p = 0.002 for CD206)." (PMID 36230752, 2022). "cDC1 cells, which are IRF8-dependent, and express CD141 and CCR7, move from the tumor site to lymph nodes, activating CD8+ T anti-tumor cells." (PMID 35269652, 2022).
tumor (continued). "We first detected the mRNA level of IRFs in PC, revealing that the level of IRF2, IRF6, IRF7, IRF8 and IRF9 were elevated in tumor tissues in PC." (PMID 35012444, 2022). "We further analyzed the relationship between IRF8 expression and the clinicopathological variables of HCC patients and found that IRF8 negatively correlated with serum AFP level and tumor size." (PMID 35845349, 2022). "It was shown that IRF8, PU.1, and IRF4 bound to the promoter/enhancer regions of tumor suppressor genes, such as Ikaros and Spi-B, and in IRF-deficient samples, the expression of these genes was significantly reduced." (PMID 36078039, 2022). "We found that the level of IRF2, IRF6, IRF7, IRF8 and IRF9 were upregulated in tumor tissues in PC (P < 0.05)." (PMID 35012444, 2022). "With increasing levels of tumor PD-L1, the expression of transcription factors for Th1, Th2, or M1 macrophages, including NFKB1, GATA3, HIF1A, STAT4, TBX21, IRF8, and STAT1, was downregulated." (PMID 33754038, 2021). "Despite a general loss of cross-presentation in Batf3–/– mice, cytotoxic T cells could still actively contribute to tumor surveillance through activation by nonclassical cross-presenting DCs and classical DC1s generated by Irf8 compensating for Batf3 deficiency." (PMID 34283809, 2021). "Thus, outcome of these patients likely reflects a balance between the lack of the tumor suppressor functions of IRF8 and the antitumor immune response, which in these tumors could arise partly from the elevated expression of tumor-associated antigens." (PMID 33766090, 2021). "This study also found that high IRF8 expression in the AML cell line OCI-AML3 leads to reduced tumor size in xenograft experiments, supporting a tumor-suppressor function of IRF8 in those cells." (PMID 33673123, 2021). "Interferon regulatory factor 8 (IRF8), a transcription factor of the IRF family, acts as a tumor suppressor gene and is silenced by epigenetic mechanisms in several human tumors." (PMID 34827720, 2021). "Similar to what was observed in IRF8 KO mice, OPN is also highly expressed in the CD11b+Ly6G+Ly6C− PMN-MDSCs of tumor-bearing mice." (PMID 33203146, 2020). "Distances between cells within the tumor core were analyzed and identified the CD68+IRF8+ macrophages as the population located in closest proximity to the tumor cells with a median nucleus-to-nucleus distance of 12.3 μm." (PMID 31477692, 2019). "In the future, it would be interesting to evaluate PU.1, IRF8, and BATF3 efficacy in inducing antigen presentation directly in tumor cells." (PMID 31921109, 2019). "In our data, we found the CD68+IRF8+, CD68+CD206+, and CD68++CD163+ macrophages to be co-localized in the same tumor and were correlated with the increase of IL-1-, IL-6-, and IL-10-associated pathways, respectively." (PMID 31477692, 2019). "The left panel displays the boxplots of three genes expression profiles including IRF8, CECR1 and IL10RA for tumor and normal samples." (PMID 30210526, 2018). "In tumor-bearing mice, in which IRF8 is downregulated, neutralizing GCSF restores IRF8 levels to tumor-free mouse conditions in BM progenitors." (PMID 29593283, 2018). "For example, the transcription factor interferon regulatory factor-8 (IRF-8) is crucial for myeloid cell development and immune response and also acts as a tumor suppressor gene." (PMID 29438283, 2018). "The results showed that IL-3, IL-6, and IL-10 were differentially expressed in splenocytes from tumor bearing WT mice compared with tumor-bearing IRF-8−/−, naïve WT and naïve IRF-8−/− mice." (PMID 29438283, 2018). "In contrast, injection of recombinant TGF-β into the tumour increased both IL-9-eGFP+ CD4+ T cells and Irf8 expression in CD4+ T cells in vivo." (PMID 29233972, 2017). "The aim of the present study was to examine the prognostic value of interferon regulatory factor 8 (IRF8) expression and its effect on the development of Th17 cells in the tumor microenvironment of DLBCL patients." (PMID 28537908, 2017).
tumor (continued). "Based on earlier findings that IRF8-loss augmented tumor growth and that this malignant phenotype was inversely associated with an unexpected increase in MMP3 expression (by microarrary analysis), we hypothesized that MMP3 is downregulated by a novel IRF8-dependent mechanism." (PMID 26008967, 2015). "Altogether, we showed an inverse mechanistic relationship between IRF8 and MMP3 expression in tumor progression." (PMID 26008967, 2015). "Altogether, in several mouse tumor models, we describe a novel transcriptional mechanism of MMP3 regulation by IRF8, and showed that MMP3 expression plays an underappreciated and key role in later stages of tumor progression, including metastasis." (PMID 26008967, 2015). "The present study results demonstrated that the IRF8 gene is highly and frequently methylated in NSCLC in a tumor-specific manner." (PMID 25120651, 2014). "Functional validation further demonstrated that IL7R, IRF8, and PTPRC contribute to tumor progression by promoting immune evasion, whereas NSG1 might have tumor-suppressive effects." (PMID 41596598, 2026). "Versikine increases Interferon Regulatory Factor 8 (IRF8) expression in macrophages, promoting the generation of CD103+ CD11c+ MHCIIhi conventional dendritic cells (cDCs), which play a key role in anti-tumor immunity." (PMID 41281748, 2025). "Subsequent deletion of IRF8 in NR4A2/hA1R engineered CAR T cells abrogated the enhanced cytokine production in both serial and long-term stimulation assays and suppressed A1R driven enhanced tumor killing during the second round of long-term restimulation." (PMID 40610421, 2025). "Tumor‐derived prostaglandin E2 (PGE2) plays a significant immunosuppressive role by inducing cDC1 dysfunction through EP2/EP4‐mediated cAMP signaling, which downregulates the transcription factor IRF8, critical for cDC1 function and antitumor immunity." (PMID 40667699, 2025). "This is evident where the transcription factor IRF8 is required for cancer cell antigen presentation by monocyte-derived TAMs, which was essential for promoting cytotoxic T lymphocyte (CTL) exhaustion within the tumor." (PMID 40083710, 2025). "CRISPR-mediated deletion of IRF8 in control human anti-Lewis Y CAR T cells did not significantly modulate cytokine production or expression of memory and exhaustion markers TCF-1, TIM-3 or PD-1 in unstimulated or tumor stimulated CAR T cells." (PMID 40610421, 2025). "TAM-specific IRF8 deletion restored the CTL population and inhibited BC tumor growth." (PMID 40649751, 2025). "However, the varied permeability of the blood–tumor barrier (BTB) and blood–brain barrier (BBB) limits the efficacy of IRF8-targeted treatments." (PMID 40564171, 2025). "Taken together, these findings highlight that in vivo cDC1 reprogramming mediated by PU.1, IRF8 and BATF3 is (i) sufficient to elicit antitumor immunity, (ii) protects from distal tumor growth and (iii) tumor growth after re-challenge, and (iv) the effects are independent of endogenous cDC1s." (PMID 39236156, 2024). "Our analysis shows that both ZNF671 and IRF8 exhibited significantly lower gene expressions in BCa tumors than in non-BCa tissues, indicating potential tumor suppressive roles of the genes." (PMID 38472940, 2024). "Here, we investigated whether these in vitro findings translated into an IRF8 status–driven remodeling of the TME and whether it influenced tumor growth in vivo." (PMID 38996030, 2024). "cDC1s contribute to anti-tumor immunity via production of IL-12, as well as secretion of type I and III interferon (IFN) and expression of IRF8, but tumors may suppress IRF8 dependent development of cDC1s, limiting their antitumor effects." (PMID 38261139, 2024). "However, many of the validated IRF8 targets are known to be important for antigen processing/presentation, raising the possibility that IRF8 may also play a role in the immune composition of the tumor microenvironment (TME), while its dysfunction could facilitate immune escape." (PMID 38996030, 2024).